POLR2J2 (RNA polymerase II subunit J2)
Description:
DNA-dependent RNA polymerase catalyzes the transcription of DNA into RNA using the four ribonucleoside triphosphates as substrates. Component of RNA polymerase II which synthesizes mRNA precursors and many functional non-coding RNAs. Pol II is the central component of the basal RNA polymerase II transcription machinery. It is composed of mobile elements that move relative to each other. RPB11 is part of the core element with the central large cleft (By similarity).
Synonyms: RPB11b1; HRPB11B
Tractability: PROTAC: ubiquitination databases record sites on it.
Gene: Protein-coding gene on chromosome 7 (102,665,368 to 102,671,663, reverse strand). Ensembl gene ENSG00000228049.
Subcellular location: Nucleus
Subcellular location (Human Protein Atlas): Nucleoplasm
Gene Ontology:
Molecular function: DNA-directed RNA polymerase activity; DNA binding; protein dimerization activity
Biological process: transcription by RNA polymerase II; DNA-templated transcription
Cellular component: nucleus; RNA polymerase II, core complex
Homologues: Orthologues: guinea pig Polr2j (90% identical), macaque POLR2J (90% identical), mouse Polr2j (90% identical), rat Polr2j (90% identical), zebrafish polr2j (86% identical), Drosophila melanogaster Polr2J (70% identical), Caenorhabditis elegans rpb-11 (63% identical). Paralogues in human: POLR2J3 (99% identical), POLR2J (90% identical), POLR1D (28% identical).
Diseases named in the same sentence as POLR2J2 in open-access papers:
POLR2J2 is named in the same sentence as 1 disease in open-access papers, as found by Europe PMC text mining. Sharing a sentence is not in itself a finding about the gene and the disease. The quoted sentences say what the papers report.
cervical cancer (1 paper, 2021). A primary or metastatic malignant neoplasm involving the cervix. "The result shows that POLR2J2, RBFOX3, RBMS1, ADARB1, AFF3, CSDC2 and CTIF were down-regulated in most of cervical cancer tissues compared with corresponding normal cervix tissues." (PMID 34863153, 2021).